Y_RNA (Y RNA )
Gene: Miscellaneous RNA gene on chromosome 10 (13,511,206 to 13,511,313, reverse strand). Ensembl gene ENSG00000202508.
Homologues: Orthologues: chimpanzee Y_RNA (99% identical), macaque Y_RNA (65% identical). Paralogues in human: RNY1 (80% identical), Y_RNA (80% identical), Y_RNA (79% identical), Y_RNA (78% identical), Y_RNA (77% identical), Y_RNA (76% identical), RNY1P2 (75% identical), RNY1P7 (75% identical), Y_RNA (75% identical), Y_RNA (74% identical), RNY1P16 (73% identical), RNY1P5 (73% identical), and 90 more.